CD74 (CD74 molecule)
Diseases named in the same sentence as CD74 in open-access papers (continued):
Sharing a sentence is not in itself a finding about the gene and the disease.
Autoimmunity (9 papers, 2008 to 2024). The occurrence of an immune reaction against the organism's own cells or tissues. "Identified genes include Ptpn22, previously identified as important in human autoimmunity and a potential therapeutic target, and CD74, a key modulator of B cell maturation and survival." (PMID 19578517, 2008). "We demonstrate that CD8+ T effector memory cells might drive and sustain autoimmunity via macrophage migration inhibitory factor (MIF)‐CD74 signaling to immature B cells and CC‐chemokine ligand 5 (CCL5)‐mediated recruitment of cytotoxic CD4+ T cells." (PMID 34254741, 2021). "Overexpression of CD74 plays a crucial role in preventing hyperreactivity between immature antigens and major histocompatibility complex class II as well as cell growth and survival, whereas down-regulation of CD74 is often correlated with autoimmunity and cell apoptosis." (PMID 32744317, 2020). "Although CD74 has not previously been linked to anergy, tolerance or autoimmunity, it has several biologic functions consistent with such a role." (PMID 19578517, 2008). "Notably, when focusing on individual interactions of the cDCa cluster, MHC class II-related transcripts (eg, CD74, HLA-E) were predicted to interact with surface molecules such as MIF or KLRC1 with immunomodulatory capacity and known association to autoimmunity." (PMID 34783307, 2021). "Given the expression of CD74 on monocytes/macrophages and B cells, treatment with milatuzumab may permit combined targeting of the innate and adaptive immune systems and thus may be promising for treating autoimmunity, as exemplified by successful anti-cytokine treatment." (PMID 22404985, 2012).
B cell lymphoma (9 papers, 2015 to 2026). "For example, B cell lymphomas carrying IRF8 mutations can circumvent immune detection via CD74-dependent pathways." (PMID 41597203, 2026). "Milatuzumab demonstrated potent antitumor activity in preclinical models and showed early signs of clinical efficacy in hematologic malignancies, particularly in B cell lymphomas and multiple myeloma, where CD74 is highly expressed." (PMID 41597203, 2026). "Among hematologic malignancies, B cell lymphomas exhibit particularly strong CD74 expression and dependency." (PMID 41597203, 2026). "Last, we also detected a significant increase in TFH cells in the mouse models of IRF8-mutant B cell lymphoma, which was corrected by CD74 ectopic expression." (PMID 38996030, 2024). "We concluded that in B cell lymphoma models, IRF8 KO and/or expression of mutant variants decrease CD74 and HLA-DM expression, mainly deregulating intracellular antigen processing and loading, rather than MHCII expression on the cell surface." (PMID 38996030, 2024). "The consistent expression of CD74 on normal and transformed B cells, its rapid internalization, as well as growth-inhibitory and death-inducing effects in vitro on B cell non-Hodgkin lymphoma (B-NHL) cells, brought CD74 into focus as a therapeutic target." (PMID 34638496, 2021). "The bulk of studies investigating MIF in B cell biology have stemmed from those evaluating the functional significance of the MIF/CD74 interaction in B cell lymphoma." (PMID 33324425, 2020). "We concluded that CD74 is an important mediator of IRF8 dysfunction in B cell lymphomas." (PMID 38996030, 2024). "Our in vivo model of IRF8-mutant B cell lymphoma validated this initial observation and linked it to defective antigen loading into MHCII complexes because it could be rescued with CD74 ectopic expression." (PMID 38996030, 2024). "Less clear from these findings in B cell lymphoma is whether MIF/CD74 interactions are important in de novo B cell antibody responses and/or anti-tumor immunity." (PMID 33324425, 2020). "Last, to mitigate concerns that the ectopic expression of CD74 may enhance CD4 activation irrespective of IRF8 status, and to define whether CD74 can rescue the IRF8-mutant phenotype, we tested CD74 effects on B cell lymphoma models expressing IRF8 WT, the DBD mutant N87Y, or the CTD mutant I424T." (PMID 38996030, 2024). "In murine B cell lymphoma models, which allow for in vitro (CD4 DO-11.10 cells) and in vivo functional examination of defective antigen presentation, CD74 appear to be the main “target” of IRF8 effects." (PMID 38996030, 2024). "These cancer studies use anti-CD74-based antibody-drug conjugates to increase drug uptake or monoclonal antibodies against MIF or CD74 in cancers, including metastatic colon cancer, B-cell lymphoma, and other solid malignancies." (PMID 35036405, 2021). "In our model system, ectopic expression of CD74 was sufficient to rescue the immune and clinical phenotypes detected in IRF8-mutant B cell lymphomas, but it did not significantly change the immune landscape or growth pattern of IRF8 WT B cell lymphomas." (PMID 38996030, 2024). "In summary, high CD74 expression levels in tumors, nanomolar cellular potency, and significant anti-tumor in DLBCL and MCL xenograft models support the ongoing clinical study of STRO-001 in patients with B-cell NHL." (PMID 36634212, 2023). "Expression of IRF8 mutants in murine B cell lymphomas suppressed CD4, but not CD8, activation elicited by antigen presentation and downmodulated CD74 and human leukocyte antigen (HLA) DM, intracellular regulators of antigen peptide processing/loading in the major histocompatibility complex (MHC) II." (PMID 38996030, 2024).
non-small cell lung carcinoma (9 papers, 2009 to 2025). A group of at least three distinct histological types of lung cancer, including non-small cell squamous cell carcinoma, adenocarcinoma, and large cell carcinoma. "Recent study on non-small cell lung cancers suggested that the co-expression of MIF and its receptor CD74 is associated with greater tumor vascularity and greater of angiogenic CXC chemokines." (PMID 19602232, 2009).
colitis (8 papers, 2020 to 2024). Inflammation of the colon. "Using a combination of genetic knock-out, bone marrow chimera mice, chemical, non–chemically-induced, acute, and chronic mouse models of colitis, CD74 was found to be essential for mucosal healing in colitis-associated injury." (PMID 32655566, 2020). "It has been recently demonstrated that CD74 expression in IEC is crucial for inflammation-induced mucosal healing in different murine colitis models, further supporting a protective role of IL-27 in IEC as previously demonstrated by us." (PMID 37818353, 2023). "Consistent with our human findings, CD74 expression was enhanced in intestinal epithelium of mice with DSS-induced colitis as analyzed by flow cytometry and immunohistochemical staining." (PMID 32004754, 2020). "During the colitis phase, WT and CD74−/− mice showed comparable clinical disease, as evidenced by similar body weight loss." (PMID 32004754, 2020). "By using distinct but complementary chemical and non–chemically induced mouse models of colitis with genetic and antibody neutralization approaches, we found that CD74 signaling was necessary for gut repair." (PMID 32004754, 2020). "By using human studies, cellular models, and mouse models, we have uncovered a mechanism of intestinal healing during colitis involving CD74 signaling that promotes intestinal repair." (PMID 32004754, 2020). "In a separate but complementary non–chemically induced mouse model of colitis, we took advantage of the amebic colitis and repair model to further examine the role of CD74 during intestinal inflammation and regeneration." (PMID 32004754, 2020). "To test the hypothesis that CD74 may function to promote recovery and mucosal healing in colitis, we treated mice with 7 days of DSS to induce inflammatory damage followed by a recovery period." (PMID 32004754, 2020). "Thus, our data indicate that CD74 depletion leads to impaired healing in colitis." (PMID 32004754, 2020). "Therefore, it was not too surprising to find that CD74 deficient mice had normal colon, histology, and barrier integrity, and lacked spontaneous colitis in the absence of pathologic insults." (PMID 32655566, 2020). "Specifically, ICI-colitis is enriched in mucosal Th1 effector cells that highly express IFNγ inducible genes such as STAT1, CD74, and GBP1/5 when compared to healthy controls and colitis-naïve patients." (PMID 39247203, 2024). "Interestingly, CD90+CD74+ inflammatory fibroblasts express IL-33 and are increased in DSS-induced colitis, indicating this population is likely responsible for the increases in Il33 in acute colitis induced by epithelial damage." (PMID 33953267, 2021). "First, we did not observe a significant change in CD74 expression by immune cells during colitis as analyzed by flow cytometry." (PMID 32004754, 2020). "We studied the characteristics of CD74 protein expression in human IBD and experimental colitis." (PMID 32004754, 2020). "Here, we studied the role of CD74 signaling in mucosal healing during colitis, finding that CD74 activation does not drive tissue destruction, but protects the host by promoting mechanisms that restore epithelial lining and mucosal integrity during intestinal inflammation." (PMID 32004754, 2020).
glomerulonephritis (8 papers, 2010 to 2023). A renal disorder characterized by damage in the glomeruli. "Small molecule MIF antagonists also resulted in reduced glomerulonephritis and interstitial inflammation, lower levels of CD74+ and CXCR4+ leukocyte recruitment and decreased circulating TNF-α." (PMID 30787934, 2019). "CD74 expression is increased in tubular cells and/or glomerular podocytes and parietal cells in human metabolic nephropathies, polycystic kidney disease, graft rejection and kidney cancer and in experimental diabetic nephropathy and glomerulonephritis." (PMID 26441987, 2015). "However, CD74 may also contribute to disease for glomerulonephritis and kidney cysts." (PMID 26441987, 2015). "Furthermore, in the cluster of the podocyte, three glomerulonephritis related genes named FXYD5, CD74 and B2M were found." (PMID 33754492, 2021). "More recently, the inhibitor of MIF/CD74 interactions RPS19 prevented the development of glomerular crescents, necrosis, inflammation, renal dysfunction, proteinuria, and the upregulation of MIF and CD74 in anti-GBM glomerulonephritis." (PMID 26441987, 2015).
leukemia (8 papers, 2015 to 2026). A malignant (clonal) hematologic disorder, involving hematopoietic stem cells and characterized by the presence of primitive or atypical myeloid or lymphoid cells in the bone marrow and the blood. "Nonetheless, these observations collectively suggest leukemia-specific proximity of CD74+CD68+ cells and CD34+ primitive cells, and a potential support role for RECs in AML regeneration that forms the basis of functional testing." (PMID 38582086, 2024). "Based on the transcriptional signature, HLA class II histocompatibility antigen gamma chain (Cd74) is highly expressed in PKH-retaining leukemia cells." (PMID 38922758, 2024). "Eight genes (BAALC, CD14, CD34, CD74, DNTT, HLA-DRA, IRF8, and MN1) were all associated with “leukemia” (P = 1.15 × 10−4), “acute myeloid leukemia” (P = 9.37 × 10−3), and “proliferation of myeloid cells” (P = 0.044)." (PMID 26517675, 2015). "Interestingly, the rare CD74-PDGFRB oncogenic fusion remains relevant to cancer in exclusively leukemia." (PMID 37958963, 2023). "CD74, TNFRSF1B, and ADAM8 all have important roles in the immune system and have enrichment for mRNA expression on candidate cells of origin for NHL and leukaemia." (PMID 38750076, 2024). "Collectively, our findings reveal that the identified slow-cycling leukemia cell population represents an LSC population, and CD74+ leukemia cells possess stemness properties, suggesting that CD74 is a candidate LSC surface marker." (PMID 38922758, 2024). "Furthermore, cell surface CD74 was identified to be highly expressed in LSCs of AE9a mice and CD34+ human leukemia cells." (PMID 38922758, 2024). "CD34+ areas had higher CD74 and CD68 expression as compared with CD34− areas, while this pattern was absent in healthy tissues, confirming a leukemia-specific proximity of RECs and CD34+ cells." (PMID 38582086, 2024).
lung adenocarcinoma (8 papers, 2018 to 2025). A carcinoma that arises from the lung and is characterized by the presence of malignant glandular epithelial cells. "The expression levels of CD74 in tumor tissues and normal tissues were compared based on the RNA-seq data of lung adenocarcinoma (LUAD) and lung squamous cell carcinoma (LUSC) patients from the TCGA database." (PMID 40470045, 2025). "In the human lung cell dataset, gene CD74 has been shown to play an important role in eliciting immune response in lung adenocarcinoma." (PMID 37697330, 2023). "Studies have found CD74 fusion proteins in a range of cancers, including lung adenocarcinoma, inflammatory breast cancer, and pediatric acute lymphoblastic leukemia." (PMID 37958963, 2023). "Absence of the p41 CD74 isoform seems to prevent associations between CD74 and CD44 in human lung adenocarcinoma-derived cells." (PMID 36142162, 2022). "The expression of these lncRNAs and CD74 was validated in lung adenocarcinoma biopsies." (PMID 39001552, 2024). "Therefore, the identified lncRNAs and CD74 could be employed as novel predictive biomarkers or therapeutic targets to increase the effectiveness of targeted therapy and improve the clinical outcomes of patients with lung adenocarcinoma." (PMID 39001552, 2024). "In the present study, RT–qPCR analysis confirmed CD74 expression in osimertinib-induced DTP cells from cell lines and lung adenocarcinoma biopsies." (PMID 39001552, 2024).
osteosarcoma (8 papers, 2019 to 2025). A usually aggressive malignant bone-forming mesenchymal neoplasm, predominantly affecting adolescents and young adults. "Though HLA-DM-α was identified as a prognostic biomarker in pediatric osteosarcoma in the current study, an investigation of the underlying mechanism, which may be particularly associated with CD74, is further required." (PMID 38256356, 2024). "In conclusion, our research identified three novel metastasis-related DEGs associated with the survival of pediatric osteosarcoma patients: C1QA, CD74, and HLA-DMA." (PMID 38256356, 2024). "MIF inhibitor 4‐IPP interrupted the MIF/CD74‐induced NF‐κB/P‐TEFb complex‐mediated c‐Myb transcription in osteosarcoma." (PMID 35060345, 2022). "CD74 was hypomethylated in osteoblast and hypermethylated in osteosarcoma cells as compared to DNA methylation patterns in 19 osteosarcoma cell lines and 2 normal osteoblasts in the GSE36002 datasets." (PMID 34957096, 2021). "CD74 is relatively low expressed in osteosarcoma tissue as compared to normal bone tissue; of the 70 osteosarcoma tissue samples, 73% had low expression of CD74." (PMID 34957096, 2021). "Consistent with the bioinformatics analysis results, hsa_circ_0001753 was significantly downregulated, hsa_miR_760 was significantly upregulated and CD74 was significantly downregulated in the osteosarcoma cell lines compared to the osteoblast cell line." (PMID 34957096, 2021). "The prognostic biomarkers C1QA, CD74, and HLA-DMA for pediatric metastatic osteosarcoma were identified using RNA-sequencing data (level 3) associated with clinical information from the TARGET-osteosarcoma dataset." (PMID 38256356, 2024). "Given that the downstream pathway of MIF/CD74 in osteosarcoma is unknown, we used rhMIF and CD74 neutralizing antibodies to verify the effect of MIF/CD74 on NF‐κB pathway." (PMID 35060345, 2022). "Our research initially explores the role of MIF/CD74 in osteosarcoma." (PMID 35060345, 2022). "A Cox regression analysis and KM survival analysis were performed to screen survival-related central DEGs based on the osteosarcoma project of the TARGET database, and three survival-related central DEGs were identified (C1QA, CD74, HLA-DMA)." (PMID 38256356, 2024). "The methylation rate of CD74 promoter DNA in osteoblasts was 96.7%, compared to 82.2% for U2OS, 91.1% for MG63 and 98.9% for HOS in the osteosarcoma group." (PMID 34957096, 2021). "In addition, through CellChat analysis,we found that HVECs in osteosarcoma secrete molecules such as MIFand APP, which interact with macrophage surface molecules or complexessuch as CD74 and CD44." (PMID 40834268, 2025). "In our study, we identified CD74 as a survival-related biomarker for the prediction of a positive prognosis, with a relatively high expression in non-metastatic pediatric osteosarcoma patients." (PMID 38256356, 2024). "Targeting the MIF-CD74 axis, known for affecting tumor survival and immune responses, offers potential for immunotherapy, especially considering CD74’s link to a better prognosis in non-metastatic osteosarcoma." (PMID 38256356, 2024). "The present study delves into the intricate roles of C1QA, CD74, and HLA-DMA, exploring their interactions within the tumor microenvironment and their implications for the immunotherapy response, thereby providing new insights into the treatment of pediatric osteosarcoma." (PMID 38256356, 2024). "Notably, C1QA and CD74 exhibited higher expression in non-metastatic osteosarcoma cases, suggesting a potential role in disease progression." (PMID 38256356, 2024).
triple-negative breast carcinoma (8 papers, 2019 to 2024). An invasive breast carcinoma which is negative for expression of estrogen receptor (ER), progesterone receptor (PR), and human epidermal growth factor receptor 2 (HER2). "CD74 has also been linked to metastasis in triple negative breast cancer." (PMID 30726216, 2019). "In the current study, we investigated the role of CD74 in the regulation of the immunosuppressive tumor microenvironment (TME) in triple-negative breast cancer (TNBC)." (PMID 39576827, 2024). "Furthermore, we showed that CD74 is involved in the uptake of rTIMP‐1 by the triple negative breast cancer cell line, MDA‐MB‐231, and that this binding effects Akt signaling, which can lead to various cell responses." (PMID 37081824, 2023). "Triple-negative breast cancer (TBNC) is the most aggressive subtype, characterized by the infiltration of immune cells expressing high levels of CD74 to the tumor microenvironment." (PMID 39576827, 2024).
viral infection (8 papers, 2010 to 2025). "VP1 expression increased in CD74KO cells, which indicated that CD74 deficiency resulted in an increase of viral infection." (PMID 37409968, 2023). "The interaction between CD74 and EV-D68 may determine the outcome of viral infection." (PMID 37409968, 2023). "In addition to these functions, CD74 plays an important role in viral infection." (PMID 37409968, 2023). "In Class1, the viral infection pathways (e.g., HSV-1, EBV) and antigen presentation (e.g., HLA-DRB1/DQB1/C, CD74, CTLA4, GZMB, PRF1) were primarily enriched." (PMID 41394852, 2025). "BAY-M2d induced multiple antiviral genes (TLR7, CD74, CES1, HLA-DOA, CD209, and CMPL2), the products of which may be involved in resistance to viral infections." (PMID 40129989, 2025). "By cell sorting according to CD74 levels prior to infection, we show that this is likely not the case; instead, these changes seem to be induced by viral infection." (PMID 31967545, 2020). "Nevertheless, the potential action of immuno-reactive mechanisms during tumorigenesis mediated by the viral infection itself does not weaken the genetic argument brought forward through the identification of Cd74 as a CIS for involvement of the Cd74 locus in the tumorigenic process." (PMID 20416035, 2010).